ACLY (ATP citrate lyase)
Diseases named in the same sentence as ACLY in open-access papers (continued):
Sharing a sentence is not in itself a finding about the gene and the disease.
tumor (continued). "The results revealed that ARHGEF3 knockdown attenuated tumor growth and obviously reduced tumor weight and volume, but ACLY overexpression could alleviate the tumor-inhibiting effects of ARHGEF3 knockdown." (PMID 36241648, 2022). "Moreover, ATP citrate lyase (ACLY) is upregulated in hypoxic tumor cells and seems to be a target gene of HIF-1α." (PMID 34071836, 2021). "On the contrary, inhibition of ACLY suppresses tumor growth and EMT 62,63." (PMID 32641978, 2020). "Interestingly, ACLY knockdown suppresses cell proliferation in several tumor cell lines, decreasing intracellular signaling (e.g., MAPK and Akt) in response to extracellular stimuli." (PMID 32812201, 2020). "Importantly, ACLY expression and activity has been found to be aberrantly expressed in many tumours (e.g. glioblastoma, colorectal cancer, breast cancer and others) and its inhibition correlated to repression of tumour proliferation and apoptosis." (PMID 32666259, 2020). "In vivo and in vitro studies all prove the key role of ACLY in the evolution of tumor." (PMID 32047547, 2020). "Therefore, enhanced ACLY activity in tumor cells serves to avoid the accumulation of citrate to ensure glycolysis flux and cell proliferation." (PMID 31569510, 2019). "Furthermore, increased Ki67 staining in tumor sections, which is indicative of higher proliferation rate, was observed upon caspase-10 knockdown, while simultaneous knockdown of ACLY or GCN5 significantly reduced the extent of staining." (PMID 31534141, 2019). "More importantly, it is now thought that ACLY expression may play an important role in both tumor metabolism and tumorigenesis." (PMID 31077215, 2019). "Furthermore, in mouse tumor models, metabolic stress-induced caspase-10 downregulates ACLY levels which results in reduced tumor progression and metastasis." (PMID 31534141, 2019). "Inhibiting ACLY at the genetic level or pharmacologically significantly suppresses tumor growth." (PMID 29784041, 2018). "As ACLY is highly expressed in many tumor tissues, relative to healthy controls, it may be a potential drug target." (PMID 29342092, 2018). "High glucose has been shown to induce ACLY acetylation at lysine 540, 546, and 554 by p300/CBP-associated factor (PCAF) acetyltransferase to prevent ACLY from ubiquitylation and degradation, which in turn promotes de novo lipid synthesis and tumor growth." (PMID 30283496, 2018). "We found that a progressive induction of FASN and ACLY occurred in tumor and para-tumor." (PMID 30591064, 2018). "Steeg et. al. have suggested that phosphorylation of ACLY by the Nm23-H1 metastasis suppressor may play a role in limiting migration and invasion of tumor cells." (PMID 28412757, 2017). "They reported that miR-22 could be a tumour suppressor because targeting ACLY leads to inhibition of lipid metabolism and consequent cell proliferation and migration." (PMID 28272374, 2017). "Additionally, miR-22 functions in human cells during apoptosis — a process which is known to be differentially regulated between male and female blastocysts, suppressing tumor growth through inhibition of ATP citrate lyase." (PMID 28421107, 2017). "The downregulated effect of ACLY mediated by miR-22 may decrease the common intermediates expressions in the mevalonate pathway, and therefore lead to the suppression of tumor cell invasion and metastasis." (PMID 27317765, 2016). "Furthermore, it has been reported that ACLY inhibition with chemical inhibitors or siRNA can suppress tumor cell proliferation and induce apoptosis in vitro and in vivo." (PMID 25890184, 2015). "ENO1 glycolytic activity is strongly associated with increased ATP citrate lyase expression in gliomas, thus ENO1 may act as a metabolic tumor promoter conferring a selective growth advantage onto ENO1-overexpressing tumor cells." (PMID 24650096, 2014).
tumor (continued). "Upregulation of ACLY activity in tumor cells expressing activated Akt could suppress fatty acid oxidation (through increased acetyl-CoA and malonyl-CoA production), thus supporting the significant requirement for lipid synthesis in proliferative cell states." (PMID 21049007, 2010). "Moreover, ACLY inhibition by siRNAs or the selective inhibitor SB-204990 suppresses the growth and survival of tumour cells in vitro and in vivo." (PMID 19352381, 2009). "Therefore, ACLY inhibitors are highly important for tumor control." (PMID 39984452, 2025). "Although our data strongly support ACLY as the principal target of EVT0185 in driving tumour immunogenicity, it remains possible that other targets may be important as we found that this compound also reduced acetate incorporation into fatty acids and sterols, an effect that was independent of ACLY." (PMID 40739358, 2025). "As reductions in ACLY in clinical datasets are also associated with lower tumour burden and increased B cell infiltration, further studies investigating whether pharmacological inhibition of ACLY also increases immunosurveillance and reduces tumour burden in clinical populations will be important." (PMID 40739358, 2025). "Despite these advances, challenges remain: tumor-intrinsic heterogeneity (e.g., variable ATP-citrate lyase expression) may limit efficacy in ATP-citrate lyase-low tumors, and strain-specific microbial engineering (to boost pentanoate production) requires refinement to avoid interpatient variability." (PMID 41181090, 2025). "Interestingly, another two studies demonstrated that USP13 could promote tumor progression by deubiquitinating Myc, ACLY and OGDH31, 32, indicating the opposite role of USP13 in tumor progression or inhibition." (PMID 37151889, 2023). "Furthermore, to detect whether overexpression of ACLY could rescue the loss of tumor formation in ARHGEF3-deficient cells, A549 stable cell lines with ARHGEF3 knockdown combined with ACLY overexpression were constructed." (PMID 36241648, 2022). "Since the AKT/mTOR pathway is known to play a central role in the regulation of cell lipid metabolism, we hypothesised that blocking ACLY will reduce lipid synthesis and subsequently prevent tumour cell resistance to TKI therapy, enhancing its antitumor efficacy." (PMID 36064336, 2022). "Therefore, inhibition of ACLY activity or interference with ACLY can effectively inhibit the ab initio synthesis of lipids and histone acetylation, thereby inhibiting tumor cell growth, making ACLY targeting for tumor inhibition a potential research hotspot." (PMID 36425653, 2022). "Notably, mice implanted with the USP22-overexpressing MHCC-97L cells formed larger tumors compared to those implanted with the control MHCC-97L cells; however, MHCC-97L cells with simultaneous USP22 overexpression and PPARγ, ACC or ACLY knockdown showed lower tumor growth rates." (PMID 35449157, 2022). "Interestingly, the metabolic role of ACLY may be linked to cell cycle dysregulation by its binding to low-molecular-weight (LMW) cyclin E, a tumour-specific isoform of cyclin E, to enhance ACLY function." (PMID 35448537, 2022). "In the case of SIRT6, the two-pronged regulation of both histone deacetylation and ACLY-dependent histone acetylation may help maintain the stability of tumor suppressive gene expression programs and protect against potential effects of metabolic fluctuations on SIRT6 or ACLY activity." (PMID 34573442, 2021). "During tumor development, lipid associated alterations include an increase in lipogenic enzymes expression such as fatty acid synthase (FASN), acetyl carboxylase (ACC), stearoyl-CoA desaturase (SCD), ATP citrate lyase (ACLY), and an increase in the synthesis and uptake of cholesterol." (PMID 30913248, 2019). "However, there are few reports about the specific role of ACLY in the process of tumor metastasis." (PMID 31511060, 2019).
tumor (continued). "Distinctive elevation of ACLY expression and activity has been reported in lung, ovarian, prostate, bladder, breast, liver, stomach, and colon cancers, and its inhibition by siRNAs or the selective inhibitor SB-204990 suppresses the growth and survival of tumor cells in vitro and in vivo." (PMID 25890184, 2015). "Indeed, reactivating PK, PDH, and inhibiting other up-regulated enzymes (ATP citrate lyase), may reset the system, reversing a hybrid situation favorable to stem cells and then to tumor cells." (PMID 25247026, 2014). "Moreover, this could be associated to an upstream inhibition of aconinase by NO, or more probably to a blockade of isocitrate dehydrogenase, which favors in tumor cells, the citrate efflux from mitochondria, and the ATP citrate lyase route." (PMID 21649891, 2011). "By targeting enzymes such as LDHA, GLUT1, HK2, PKM2, GLS1/2, FASN, ACLY and ACC, researchers have demonstrated the feasibility of disrupting tumor bioenergetics and biosynthetic machinery." (PMID 40941984, 2025). "ATP Citrate Lyase (ACLY), which links glucose metabolism to lipid synthesis, is ubiquitinated by the CUL3-KLHL25 E3 ligase, suppressing tumor growth by reducing lipid production." (PMID 40370434, 2025). "Regulators of the lipid metabolism pathway, including ATP carboxylase cleavage enzyme (ACLY), acetyl‐CoA synthetase (ACSS), and fatty acid synthase (FASN), play important biological roles in tumor metabolic reprogramming." (PMID 41346571, 2025). "has shown that AR-resistant tumor cells promote lipid synthesis by upregulating the expression of fatty acid synthase (FASN) and ATP-citrate lyase (ACL), thereby meeting the demands of rapid proliferation and membrane structure." (PMID 40008000, 2025). "The conversion of glucose to pyruvate in glycolytic tumor cells controls acetyl-CoA levels via pyruvate dehydrogenase (PDH) and ATP-citrate lyase (ACLY), among other enzymes, so that it can enter mitochondria or be converted to lactate." (PMID 40581650, 2025). "Knockdown of ACLY or ACC strongly reduced tumor growth, whereas knockdown of FASN1, one of the three Drosophila FASN enzymes, marginally reduced tumor growth." (PMID 40822358, 2025). "Consistently, IHC assays confirmed decreased expression of FASN, ACLY, and SCD in tumor tissues derived from VPS72 knockdown cells." (PMID 40305746, 2025). "Specifically, the activation of this pathway influences the activities of key enzymes such as HK2, ATP-citrate lyase (ACL), and the stabilization of hypoxia-inducible factor 1-alpha (HIF1a), ultimately enabling the tumor cells to meet their energy needs." (PMID 38479191, 2024). "To explore the effect of the ACLY inhibitor BMS‐303141 on the growth of xenograft tumours in nude mice, we established subcutaneous tumour model using human ESCC cells KYSE150, and then BMS‐303141 was used to treat the tumour." (PMID 38426936, 2024). "Stepwise investigation revealed that ACLY overexpression significantly promoted the expression of lipid synthesis‐related proteins in ESCC cells and tumour tissues." (PMID 38426936, 2024). "The activity of enzymes responsible for lipogenesis, such as ATP citrate lyase (ACLY) and fatty acid synthase (FAS), is enhanced in tumor cells." (PMID 39409945, 2024). "Consistently, a significant decrease in the mRNA levels of PPARa, ACLY, FASN, ACSL1 and ACSL5 was observed in the livers of C26 tumor-bearing mice compared with control mice." (PMID 38245529, 2024). "FA metabolism-related enzymes (SREBP1, ACLY, ACSL, ACC, FASN, SCD1, etc.)regulate ROS, EMT, MMPs, and angiogenesis in tumor cells, thereby promoting CRC metastasis." (PMID 39103344, 2024).
tumor (continued). "ATP citrate lyase (ACLY), as a key enzyme in lipid metabolism, plays an important role in energy metabolism and lipid biosynthesis of a variety of tumours." (PMID 38426936, 2024). "In conclusion, our preliminary results suggest that ACLY inhibitor BMS‐303141 suppresses cell proliferation, migration, invasion, lipid synthesis and the growth of xenografted tumour in ESCC cells, whereas ACLY overexpression displays the opposite effects." (PMID 38426936, 2024). "The critical role of DNL enzymes in regulating tumorigenesis has been shown through genetic evidence from several studies including the knockdown of ACLY, ACC, FAS, and SCD in various tumor types." (PMID 37958642, 2023). "We observed that the total ACLY, pACLY, ACC1, and FASN expressions were increased in the Cr-tumor tissue as compared to the normal adjacent tissues." (PMID 38069382, 2023). "ACLY, a key enzyme in the production of acetyl-CoA, serving as a substrate for DNL, supports tumor growth and confers resistance to vemurafenib in melanoma treatment." (PMID 37700339, 2023). "Subcutaneous tumours derived from CAND1 knockdown cells in a xenograft nude mouse model also exhibited downregulation of FASN, ACC1 and ACLY, enhanced oil red O staining and an increase in TAG content." (PMID 37837399, 2023). "The expression of ACLY has a significant upregulation trend in CS5 of CRC, CS2 of LC, CS3 of OV, CS3 of PDAC, and CS4 of SCC in the tumor tissue single-cell transcriptome." (PMID 37958642, 2023). "The critical enzymes for synthesizing acetyl-CoA, including adenosine triphosphate (ATP)-citrate lyase (ACLY), acetyl-CoA synthetase 1 (ACSS1), and acetyl-CoA synthetase 2 (ACSS2), are observed to have important effects in promoting tumor progression." (PMID 37122003, 2023). "In contrast, EFNA3 contributes to tumor cell self-renewal, proliferation and migration in HCC under hypoxia via SREBP1/ACLY-mediated metabolic rewiring in HCC." (PMID 36052169, 2022). "The content of both ATP citrate lyase (ACYL) and fatty acid synthase (FAS), which are involved in the synthesis of FA, increased significantly in tumor biopsies when compared to NAT." (PMID 35534478, 2022). "To assess the correlation between ACLY expression and clinicopathology in HCC, we retrospectively evaluated 52 patients with HCC, and measured ACLY expression (by IHC staining) in tumor tissue after biopsy." (PMID 35154461, 2022). "In this setting, PI3K/Akt and ACLY activate the canonical WNT/β-catenin pathway, which promotes EMT and the development of fibrotic tumor stroma, as well as exhaustion of immune response and cell cycle progression." (PMID 34205414, 2021). "Calcium hydroxycitrate in its turn is a potential inhibitor of ATP citrate lyase (ACL) and thus is expected to decrease fluxes to lipid production, thus limiting a crucial anabolic pathway for highly proliferative tumor cells." (PMID 34073567, 2021). "Tumor cell surface GRP78 of activated α2-macroglobulin signals regulate tumor cell proliferation by inducing and activating ACLY and ACSS1 expression to generate acetyl-CoA." (PMID 35004688, 2021). "Then, we further analyzed the correlations between clinicopathological features and ACC1, ACLY and FASN mRNA levels in surgical PTC tumor tissues." (PMID 34158007, 2021). "This Akt-ACLY signaling has been reported to be inhibited by treatment of statins and BET inhibitors which showed suppression of PDAC cell proliferation and tumor growth." (PMID 34603386, 2021). "While in CCRCC, upregulated-ATP citrate lyase (ACLY)-mediated fatty acid synthesis and lactate dehydrogenase A (LDHA)-mediated glycolysis provided ATP for CCRCC tumor cells growth." (PMID 32127786, 2020). "ACLY further not only serves as a bridge between the TCA cycle and fatty acid synthesis, a critical step in the modified metabolic cycle of tumor cells, but also involves in multiple pathways." (PMID 31077215, 2019).
tumor (continued). "In contrast, HUH7 cells showed a higher expression of 98 metabolic targets upregulated in tumours (e.g. HK2, PKM, PSPH, GLUL, ASNS, and fatty acid synthesis enzymes ACLY, FASN)." (PMID 30176945, 2018). "The lipogenic genes acetyl-CoA carboxylase (ACC), ATP citrate synthase (ACLY) and FASN have been shown to be up-regulated in various tumours." (PMID 30111611, 2018). "A surprising implication of this study is that acetate regulates the expression of ACLY and ACSS1 through a feed forward activation of AKT signaling to maintain acetyl-CoA production which drives histone acetylation and tumor proliferation." (PMID 29296215, 2017). "ACLY was required for LMW-E mediated transformation, migration and invasion of breast cancer cells in vitro along with tumor growth in vivo." (PMID 28399876, 2017). "Similar protein expression patterns of ACLY, PCNA and Ki-67 were revealed in the GFP positive tumor tissues by IHC staining." (PMID 27317765, 2016). "In the mice models of the four tumors, consistent with the decline of ACLY, evident lower levels of FASN and HMGCR expression were revealed by IHC staining after the anti-tumor treatment of miR-22." (PMID 27317765, 2016). "Our significant finding indicated that two SNPs in ACLY gene had a clear effect on OS and RFS of CRC patients with advanced stage tumor." (PMID 25890184, 2015). "We show that the inhibition of ACLY, ACC1 or ETV4 paradoxically allows tumor cells to survive better under hypoxia." (PMID 26452058, 2015). "To evaluate for downstream effects on tumor cell metabolism, we monitored the activation status of a substrate of AKT, ATP-citrate lyase (ACL) after SC-66 treatment." (PMID 24705275, 2014). "Consistent with this premise, tumor cells most sensitive to these agents exhibit over expression of TCA-related discriminating genes, IDH3A, IDH1, IDH3G, ACO2 and ACLY." (PMID 23056181, 2012). "Tumor cells typically maintain de novo lipid synthesis and membrane biogenesis by upregulating the expression of various metabolic enzymes, such as fatty acid synthase (FASN), acetyl-coa carboxylase (ACC), and ATP-citrate lyase (ACLY)." (PMID 41236698, 2025). "Mechanistically, lactate-derived acetyl-CoA facilitates fatty acid biosynthesis by activating ATP citrate lyase (ACLY) and acetyl-CoA carboxylase (ACC), thereby promoting membrane formation, energy storage, and the generation of signaling lipids essential for rapid tumor proliferation." (PMID 40948941, 2025). "Tumor cells exhibit characteristic changes in the expression levels and functional dynamics of enzymes critical for lipid metabolism, including acetyl-CoA carboxylase 1 (ACC1), ATP citrate lyase (ACLY) and fatty acid synthase (FASN)." (PMID 41169354, 2025). "Further, IHC scoring showed that the expression of ACLY, ACSS2, and PDH was higher in tumor tissues than in adjacent normal tissues, and there was no linear correlation between the expression level of ACLY, ACSS1, ACSS2, and PDH." (PMID 40791180, 2025). "ATP citrate lyase (ACLY), a target of HIF-1α, is upregulated in hypoxic tumor cells." (PMID 40813760, 2025). "Further research suggests that manipulating nuclear acetyl-CoA metabolism through enhancing nuclear-localized Acetyl-CoA synthetase 2 (ACSS2) or inhibiting ATP-citrate lyase (ACLY), to epigenetically reprogram terminal exhausted cells, improves anti-tumor responses." (PMID 41346587, 2025). "Cleavage of ACLY by Caspase‐10 decreases intracellular lipid levels and suppresses GCN5‐mediated acetylation of H3 and H4, inhibiting the expression of genes involved in tumor proliferation and metastasis." (PMID 38374872, 2024). "Reduced citrate metabolism through ACLY and FASN downregulation may correlate with altered lipid composition in vitamin C‐treated conditions, which helps the tumor to be more sensitive to gemcitabine." (PMID 38425123, 2024).